SNX13 (sorting nexin 13)
Description:
May be involved in several stages of intracellular trafficking. May play a role in endosome homeostasis (By similarity). Acts as a GAP for Galphas.
Synonyms: KIAA0713; RGS-PX1
Tractability: Antibody: UniProt places it where antibodies can reach, with high confidence. PROTAC: ubiquitination databases record sites on it; its protein half-life has been measured.
Gene: Protein-coding gene on chromosome 7 (17,790,761 to 17,940,712, reverse strand). Ensembl gene ENSG00000071189.
Subcellular location: Early endosome membrane
Gene Ontology:
Molecular function: phosphatidylinositol binding; phosphatidylinositol-3-phosphate binding
Biological process: intracellular protein transport; positive regulation of GTPase activity
Cellular component: early endosome; early endosome membrane
Genetic constraint (gnomAD): Loss-of-function variants: 24 observed, 66.86 expected, observed/expected ratio (o/e) 0.36, 90% interval 0.26 to 0.5. The upper end of that interval is the gene's LOEUF score, 0.5, which puts it in group 2 of 6, group 1 being the genes least tolerant of losing a copy. Missense variants: 605 observed, 691.9 expected, observed/expected ratio (o/e) 0.87, 90% interval 0.82 to 0.94. Synonymous variants: 243 observed, 221.64 expected, observed/expected ratio (o/e) 1.1, 90% interval 0.99 to 1.22.
Homologues: Orthologues: chimpanzee SNX13 (99% identical), macaque SNX13 (99% identical), rabbit SNX13 (98% identical), dog SNX13 (98% identical), pig SNX13 (98% identical), mouse Snx13 (97% identical), rat Snx13 (97% identical), guinea pig SNX13 (92% identical), tropical clawed frog snx13 (85% identical), zebrafish snx13 (80% identical), Caenorhabditis elegans snx-13 (34% identical). Paralogues in human: SNX25 (23% identical), SNX19 (18% identical), SNX14 (16% identical).
Diseases named in the same sentence as SNX13 in open-access papers:
SNX13 is named in the same sentence as 18 diseases in open-access papers, as found by Europe PMC text mining. Sharing a sentence is not in itself a finding about the gene and the disease. The quoted sentences say what the papers report.
asthma (1 paper, 2024). "Hsa_circ_0005519 (hsa_circSNX13_023), with sorting nexin-13 (SNX13) as its host gene, has been identified involving in inflammation during asthma." (PMID 38504194, 2024).
breast adenocarcinoma (1 paper, 2022). "Low nucleosome occupancy that corresponds to large nucleosome-free regions were detected at TSSs of CDT1, CRLS1, and SNX13 in chronic myelogenous leukemia cells, and at TSSs of POC1A, and CRLS1in breast adenocarcinoma cells." (PMID 36338962, 2022).
breast carcinoma (1 paper, 2024). "One of these three genes, SNX13 (Sorting Nexin 13), was associated with both post-AI E2 levels in the M3 cohort as well as sex-hormone binding globulin levels, which are likely to be relevant to breast cancer." (PMID 38965614, 2024). "Finally, we found three PGx-eQTL genes that were shared between our breast cancer GWAS and the GWAS catalog traits of cancer and hormone levels, namely SNX13, HLA-DQB2, and MORF4L1." (PMID 38965614, 2024). "Interestingly, SNX13 was shown to be downregulated in all breast cancer subtypes, but particularly in the triple-negative subtype, which may result in worse prognosis for all subtypes of- breast cancer because of a higher rate of triple negative breast cancer subtype." (PMID 38965614, 2024).
colorectal cancer (1 paper, 2022). A primary or metastatic malignant neoplasm that affects the colon or rectum. "In one study, SNX13 was linked to resistance to chemotherapy in ovarian cancer In addition, SNX13 was reported to be related to colorectal cancer migration, invasion, and metastasis." (PMID 36338962, 2022).
ovarian carcinoma (1 paper, 2022). A malignant neoplasm originating from the surface ovarian epithelium. "Among candidate gene set, POC1A and SNX13 have limited information on their association with ovarian cancer." (PMID 36338962, 2022). "As a result, six genes (CDT1, CNIH4, CRLS1, LIMCH1, POC1A, and SNX13), and two miRNAs (mir-147a, and mir-103a-3p) were suggested as novel candidate prognostic biomarkers for ovarian cancer." (PMID 36338962, 2022).
SNX13 also shares sentences with these, for which no sentence is quoted: cancer (2 papers); adenocarcinoma (1); autism (1); cervical carcinoma (1); chronic myelogenous leukemia (1); depression (1); gastric cancer (1); heart failure (1); neurological disease (1); schizophrenia (1); skin melanoma (1); triple-negative breast carcinoma (1); tumor (1).